IL4 (interleukin 4)
Diseases named in the same sentence as IL4 in open-access papers (continued):
Sharing a sentence is not in itself a finding about the gene and the disease.
tumor (continued). "Many studies have shown that interleukin-4 can promote tumor progression and metastasis by affecting apoptosis of tumor cells." (PMID 31871935, 2019). "For example, tumor-derived cytokines, including IL-6 and IL-1β, as well as cytokines released from activated T cells, such as IL-4 and IL-10, develop common myeloid progenitor cells into MDSCs." (PMID 31048856, 2019). "In the current study, 4/21 ICR-CAR T cells achieved rapid tumor eradication in the presence of IL-4, with a comparable efficiency to that of 4/7 ICR-CAR T cells." (PMID 31379876, 2019). "High levels of IL-4 in the tumor niche drive the M2 polarization of TAMs and thus impair antitumor immunity." (PMID 31554795, 2019). "It is known that TH2 cytokine responses predominantly stimulate the humoral immune response through IL-4, leading to a reduction in the cytotoxic immune response and sequential tumor growth." (PMID 31737559, 2019). "To determine the long-term anti-tumor effects of 4/21 ICR-CAR T cells, we constructed tumor cells producing human IL-4." (PMID 31379876, 2019). "Our data unravel unexpected IL-4-independent functions of Stat6 in chromatin compaction in intestinal epithelial cells ultimately providing both tumor suppressive as well as tumor promoting effects in different models of intestinal tumorigenesis." (PMID 30353167, 2019). "We observed that tumor cells secrete lower levels of IL-4 after being cocultured with STAT6−/− CD11b+ cells, indicating that the pathway regulating IL-4 secretion pathway is inhibited by STAT6 deficiency in CD11b+ cells but not tumor cells." (PMID 31798581, 2019). "IL-4 is a multi-functional cytokine with anti-inflammatory and anti-tumor activity, produced by lymphocytes, basophils and mast cells." (PMID 31419243, 2019). "Studies have found that healthy mice caged with tumor-bearing mice displayed elevated serum NE levels that correlated with increased production of pro-inflammatory cytokines (IL-4, IL-5) and increased lung inflammation." (PMID 31737559, 2019). "Taken together, our data suggest that STAT6 promotes cancer cell proliferation by altering tumor-macrophage interactions and IL-4 secretion." (PMID 31798581, 2019). "After blockade of IL-4, the down-regulation of M1-associated cytokines (CXCL10, CD86, and IL-12) was observed as compared to cryo-thermal eosinophils + tumour-bearing macrophage group." (PMID 31519961, 2019). "Conversely, IL-4 induced CCL17, a chemokine associated with Treg recruitment, M2-polarized macrophages, and tumor-associated neutrophils." (PMID 30849228, 2019). "CD4+CD8αα and CD4+CD8αβ T cell clones were then stimulated for 48 h with anti-CD3/CD28 antibodies and supernatants were harvested to measure levels of antitumor Th1-type cytokines (IFN-γ, TNF-α), as well as of pro-tumor Th2-type cytokines (IL-4, IL-5)." (PMID 30984190, 2019). "The number of M2 macrophages is increased due to chemokines released from tumor cells: Il-6, IL-4, VEGF, TGF-β." (PMID 30680411, 2019). "Tumor-derived factors like IL-10 and IL-4 inhibit the production of pro-inflammatory cytokines and chemokines in macrophages and create an immunosuppressive M2-like phenotype resembling TAM." (PMID 31138333, 2019). "Pro-tumor: Accumulation of ILC2s and their cytokines, IL-33 and IL-4 contribute to immune-suppressive environment." (PMID 32117199, 2019). "Since the discovery that monocytes, cultured with GM-CSF and IL-4, differentiate into dendritic cells (DC), the idea to use ex vivo generated DC to vaccinate cancer patients against tumor antigens has been largely explored." (PMID 31611878, 2019). "IL-4 is consistently reduced in STAT6−/− CD11b+ cells compared to WT CD11b+ cells when cocultured with tumor cells." (PMID 31798581, 2019). "Here we report a novel interleukin (IL)-4 vs. IL-21 ICR (4/21 ICR) that enhanced CAR-T cell potency in IL-4+ tumor milieu via a different working-mechanism from 4/7 ICR." (PMID 31379876, 2019).
tumor (continued). "In contrast, IL-4 or IL-13 induce the M2 phenotype, which promotes tumor angiogenesis and suppresses immune responses." (PMID 31412566, 2019). "The expression of Th1 cytokines (IL-2, TNF, IFN-γ) and Th2 cytokines (IL-4, IL-5, IL-6, IL-10) were examined in frozen tumor tissues from 80 GC patients by ELISA." (PMID 31417548, 2019). "Profiling of these cells revealed a switch from an immunosuppressive Th2 to a pro-inflammatory Th1 phenotype with increased ratios of INF-y to IL-4 in tumor-infiltrating CD4+ and CD8+ memory T-cells." (PMID 30506500, 2019). "Alternative activation of macrophages mediated primarily by IL-4 leads to an array of pro-tumorigenic functions that promote tumor progression, dissemination, and inhibit response to therapy." (PMID 31555258, 2019). "Based on our study results, we support the anti-inflammatory effects of the cytokines and we think that by inhibiting the secretion of proinflammatory cytokines IL-10 and IL-4 will contribute to tumor suppression." (PMID 31351482, 2019). "Our previous study on mouse hematologic neoplasm cells indicated that a blockade of ICOS/ICOSL pathways in tumor cells led to the downregulation of IL-4 and IL-10, both of which have anti-inflammatory effects." (PMID 31143539, 2019). "The percentage of total F4/80+ macrophages was higher in IL-4 neutralizing group as compared to cryo-thermal eosinophils + tumour-bearing macrophage group." (PMID 31519961, 2019). "al, VEGF is responsible for recruitment of monocytes from the peripheral circulation, whereas IL-4 induces their differentiation into tumor-promoting M2-like macrophages." (PMID 31419243, 2019). "In some tumor cells, cytokine IL-4 can act as a pro-survival signal factor and activate downstream STAT6 to begin responsive gene transcription for anti-apoptotic activity." (PMID 30890936, 2019). "IL-4 is an anti-inflammatory cytokine and various in vitro studies have documented its anti-tumor activity on breast and colon cancer." (PMID 31582940, 2019). "In DIPG tissues, transcript-level analysis found significant expression of IL-4, IL-13, and IL-13Rα1/2, with strong differential expression of IL-13Rα1/2 in tumor versus normal brain." (PMID 29621254, 2018). "These so-called IL-15 DCs have already proven themselves superior to the classic IL-4 DCs based on their direct cytolytic activity against tumor cells and their capacity to stimulate adaptive and innate anti-tumor immunity." (PMID 29692776, 2018). "M2 macrophages, which can be induced in vitro by interleukin 4 (IL-4) and IL-13 show anti-inflammatory and tissue reparative activities, can promote tumorgenesis and tumor progression." (PMID 30274167, 2018). "Different phenotypes of macrophages often present different roles in tumor microenvironment, which are tightly regulated by factors in the tumor microenvironment including interleukin-4, interleukin-10, immunoglobulin etc.." (PMID 29861872, 2018). "This combination of modifications: (i) protected transgenic cells from the inhibitory effects of IL4, (ii) enhanced T cell expansion at the tumor site, and (iii) improved the in vitro and in vivo anti-tumor activity of transgenic cells." (PMID 29747685, 2018). "Acting as immunomodulator, IL-4 has many important roles like class switching of antibody IgE, anti-inflammatory agent and inhibition of tumor in animal model and in-vitro studies." (PMID 30046620, 2018). "The model results predicted that injecting M1 macrophages or Th1 cells, administering anti-TGF-β to reduce angiogenesis and simultaneously reducing the production of IL-4 and IL-10 is a promising strategy to eliminate a tumor." (PMID 35847834, 2018). "Previously, the importance of IL‐4 as a regulator of tumor‐initiating/cancer stem cell (CSC)‐like cells has been documented in several cancer types." (PMID 29236307, 2018). "One of the limiting factors of the tumor is the immunosuppressive cytokine network including TGF-β, IL-1, and IL-4, which are present in the tumor site." (PMID 30108584, 2018).
tumor (continued). "The reduction of IL-4 levels in mice treated with umbelliprenin can help the anti-tumor activity of umbelliprenin." (PMID 30127820, 2018). "Factors in the pancreatic cancer microenvironment, such as CSF-1, IL-4, IL-13, TGFβ and IL-10, can promote myeloid progenitor cell differentiation into monocytes and macrophages and recruit them to the tumor microenvironment." (PMID 30060755, 2018). "Resultsshowed that the protein levels of IL-4, IL-10, and IL-13 were significantly increased inthe serum of tumor-bearing mice, respectively (Ps < .05)." (PMID 29950152, 2018). "Tumor-produced TSLP has been shown to up-regulate OX40L expression on DCs, thus inducing the generation of Th2 cells that produce IL-4 and IL-13 that have been shown to promote tumor growth in breast and pancreatic cancer." (PMID 30619378, 2018). "A study has revealed that IL-13 along with Th2 cytokines such as IL-10 and IL-4 assist in the immunological tumor escape and interfere with the induction of an antitumor response." (PMID 30643796, 2018). "Tumor rechallenge selectively induced 2G.4/7ICR T cell re-expansion only at the site engrafted with IL4-producing tumor, leading to tumor rejection on that side but contralateral tumor outgrowth." (PMID 29747685, 2018). "Once the tumor is established, tumor cells secrete cytokines IL-4, IL-10, IL-13 and lactic acid, and along with the presence of CD4+ Th2 cells, cause the polarization of TAMs toward an M2-like phenotype." (PMID 30356656, 2018). "A close relationship between tumor progression and IL-4 produced by tumor-infiltrating Th2 lymphocytes has been found in several malignancies such as non-small cell lung carcinoma, breast cancer, renal cell carcinoma, prostate cancer, and others." (PMID 30154786, 2018). "Altogether, we conclude that IL‐4 is a regulator of basal‐like cells showing characteristics of tumor‐initiating cells by inducing expression of CD44." (PMID 29236307, 2018). "To next ensure that our MUC1-targeted T cells retained effector function in the suppressive tumor microenvironment, we paired our CAR with a chimeric receptor designed to harness and invert the inhibitory effects of tumor-produced IL4." (PMID 29747685, 2018). "Higher protein levels of interleukin-4,-10, and -13 were also observed in the serum or the tumor homogenates of tumor-bearingmice." (PMID 29950152, 2018). "In our study, cultured, peptide‐pulsed DCs grown in the presence of GM‐CSF and IL‐4 induced greater protection against TUBO tumours than a free peptide vaccine." (PMID 28944998, 2018). "In vivo anti-tumor activity was assessed using IL4-producing MDA MB 468 tumor-bearing mice using calipers to assess tumor volume and bioluminescence imaging to track T cells." (PMID 29747685, 2018). "The antiinflammatory factors, including IL-4, IL-10, and IL-13, inIL-33-treated tumor-bearing mice were also significantly increased." (PMID 29950152, 2018). "Tumor regression by IL-4 is exerted by augmenting antitumor effector T cell responses supported by host antigen presenting cells (e.g., granulocyte and macrophages) as well as the direct anti-proliferative action of IL-4." (PMID 29473868, 2018). "On the other hand, serum concentrations of IL-4 showed significant decrease in both tumor and normal mice on umbelliprenin compared to control group and liquid paraffin group." (PMID 30127820, 2018). "M2 polarization, induced by IL-4, takes an important role in tumor growth, development, invasion, and metastasis." (PMID 29378465, 2018). "Unlike in tissue homeostasis, the signals from the tumor microenvironment, such as TGF-β or IL-4, induce the differentiation of tumor-promoting M2 macrophages." (PMID 29558460, 2018). "IL4i1, a homolog of LAO1, is expressed by immune cells, including macrophages, T cells, and B cells, upon stimulation by IL4, and has been shown to exert immunomodulatory functions in various tumours and in response to bacterial infections." (PMID 30038322, 2018).
tumor (continued). "The cells displayed pro-inflammatory (IL-2, IL-8, and TNFα) and anti-inflammatory (IL-4 and IL-10) activities IL-2, IL-4, and IL-8 can promote the proliferation and survival of tumor cells by means of autocrine/paracrine signaling pathways." (PMID 29495627, 2018). "Following the development of an intraepithelial lesion, this macrophage phenotype is shifted towards an immunosuppressive subset by tumour-derived cytokines as IL4, IL10 and IL13." (PMID 30577495, 2018). "In general, macrophages that infiltrate tumor tissues are driven by tumor-and T cell-derived cytokines to acquire a polarized M2 phenotype characterized by production of IL-4, IL-13, IL-10, and glucocorticoid hormones." (PMID 30042333, 2018). "These treatments can be made robust with respect to pro-tumor immune cell polarization if coupled with antibodies that neutralize IL-4 and IL-10." (PMID 35847834, 2018). "On the other hand, M2-polarized macrophages activated by IL-4 dampen inflammatory responses and promote tumor cell immune evasion, invasion, and angiogenesis." (PMID 29682521, 2018). "In the TME, IL-4 is produced by tumor cells, mast cells, activated Th2 cells, eosinophils, basophils, and MDSCs." (PMID 30154786, 2018). "The augmented CD200 expression not only attenuates antigen-specific Th1 cytokines such as IFNγ and TNFα production but also direct them to acquire Th2 phenotype (expression of IL-4/IL-10 cytokines in viral and tumor pathogenesis)." (PMID 29915577, 2018). "The ratio between effector CD8+IFNγ+ and CD4+IL-4+ T cells, the latter commonly endowed with a pro-tumor ability, was tipped in favour of effector cells in the SULT2B1b-4T1 TME." (PMID 30333826, 2018). "IL-4 also acts as a survival factor on tumor cells by increasing the expression of anti-apoptotic molecules." (PMID 30042722, 2018). "The level of ALCAM transcripts was positively associated with the expression of tumor necrosis factor α (TNFα), nuclear factor-kappa B (NF-κB) p50 subunit, and interleukin (IL)-4 in tumor tissues (p < 0.001, p < 0.001 and p = 0.012, respectively)." (PMID 29315254, 2018). "Other studies also showed that cytokine IL-4 and IL-10 expression is reduced and the tumor immune response is decreased by inhibiting the expression of ICOS and its receptor, which is not conducive to activation of T cells." (PMID 29316975, 2018). "Yet, tumour cells and the irradiated tumour microenvironment also produce M2 activators (IL-4, IL-10, IL-13, TGF-β, and PGE2)." (PMID 30178305, 2018). "M2 are activated by cancer cells through IL-4, IL-10, and IL-13 production and secrete macrophage-derived EGF causing tumor cell migration around blood vessels." (PMID 30662458, 2018). "Among various cytokines involved in the regulation of CSC properties, interleukin 4 (IL-4) is known to inhibit apoptosis, enhance proliferation during metastasis, and confer resistance to chemotherapy drugs, thus promoting tumor formation and growth." (PMID 28587176, 2017). "YAP1-silencing led to the concomitant decreased expression of major oncogenic pathways including Kras, mTOR, β-catenin, and M2-promoting IL-4 and tumor-promoting IL-6 cytokines." (PMID 28241877, 2017). "Targeting IL-4Rα with a fusion protein of IL-4 and Pseudomonas exotoxin resulted in strong anti-tumor activity in vitro as well as in vivo." (PMID 28350325, 2017). "Local signals in the tumor microenvironment (IL-4, IL-6, IL-10, PGE2, CSF-1, and transforming growth factor-β, TGF-β) polarize macrophages into alternative, protumoral M2-like cells." (PMID 28197019, 2017). "Using the MMTV-PyMT model, it was found that CD4+ T helper cells can induce alternative activation of TAMs and secretion of EGF, to directly promote tumor invasion and egress from the primary tumor as a result of IL4 activation." (PMID 28883015, 2017). "In the present study, the Th2-class cytokines IL-10, IL-5 and IL4 were also decreased in response to the tumor challenge, but only in multiparous mice." (PMID 28966800, 2017).
tumor (continued). "IL-4 is an immunosuppressive cytokine in the tumor microenvironment that can promote fibrogenesis, support tumor growth and protect malignant cells from immune destruction." (PMID 29046826, 2017). "Stimulating U937 cells with IL-4 resulted in an increase in tumor growth in vivo and stimulated angiogenesis within the tumor bed." (PMID 27073100, 2017). "Another feasibile strategy to modulate tumor microenvironment signalling is to directly inhibit TGFβ, IL-10, and/or IL-4 signaling." (PMID 28331617, 2017). "Then, FLT‐1 expressing monocytes can be recruited by VEGF into the tumor and act together with the Th2 cytokine IL‐4 to promote M2 polarization of macrophages." (PMID 27974353, 2017). "This supports the (micro-array) results, stating that IL-15 DCs are superior in the recruitment of antitumor effector cells as compared to IL-4 DCs, which endorses the suitability of IL-15 DCs as a tumor vaccine." (PMID 28099143, 2017). "Third, IL-4 protein is found abundantly in the surroundings of tumor cells, secreted by infiltrating lymphocytes as well as by the tumor cells themselves." (PMID 28350325, 2017). "Lymphocytes, like T-lymphocytes who are able to secret interleukin-4 and -5 in tumor microenvironment, have an anti-tumor activity by inducing cytotoxic cell death and inhibiting tumor proliferation." (PMID 29133845, 2017). "Mechanistically, our and other labs noticed that IL-10- or IL-4-stimulated macrophages export iron to accelerate tumor growth by supplying iron to actively proliferating tumor cells." (PMID 28979267, 2017). "Since anti-IL-25 treatment resulted in a reduction of IL-4-producing Th2 cells, we then examined the polarization of tumor macrophages in the MMTV-PyMT tumor model." (PMID 27909985, 2017). "They reverted the inhibitory effect of the IL4 cytokine by creating a double input system (target antigen and IL4) that promoted selective expansion of transgenic T cells only in the tumor microenvironment." (PMID 28106050, 2017). "Th2 cells generate IL-4 and IL-13 to promote tumor growth by stimulating tumor cell proliferation or promoting tumor cell resistance to apoptosis." (PMID 27935860, 2017). "This is confirmed by functional data indicating an enhanced recruitment of granzyme B+ effector lymphocytes by IL-15 DCs, as compared to IL-4 DCs, and subsequent superior killing of tumor cells by the migrated lymphocytes." (PMID 28099143, 2017). "We now explore the tumor-free stability condition and the dynamics of periodically pulsed therapy when IL-4 is administered independently." (PMID 29250133, 2017). "The paracrine origin of IL-4 from the cells resident in tumor microenvironment have also been reported." (PMID 28927416, 2017). "We further analyzed the percentages of IL-17A-, IL-6-, IFN-γ-, IL-4- and GM-CSF-producing Th cells (T helper cells) in tumor-infiltrating lymphocytes (TILs) from H7 tumor-bearing mice treated with Sc-4F or L-4F." (PMID 29245934, 2017). "In some cancers, including breast 72, gastric 73 and pancreatic cancer 74, 75, Th2 cells and associated cytokines [IL‐4, IL‐13, Thymic stromal lymphopoietin (TSLP)] contribute to tumour progression." (PMID 28032353, 2017). "Surprisingly, increased levels of IL-4 were also detected in the micromilieu of different tumors produced either by tumor cells themselves or by infiltrating lymphocytes." (PMID 28350325, 2017). "High levels of IL-4 in the tumour microenvironment have been correlated with the grade of malignancy and tumor resistance to apoptosis." (PMID 28117391, 2017). "Herein, we provide an overview of the current understanding of the role of the best-validated cytokines involved in tumor progression, IL-1, IL-4 and IL-6; in addition to IL-2 cytokines family, which is known to promote tumor eradication by immune cells." (PMID 28927416, 2017).